BIN1 (bridging integrator 1)
Diseases named in the same sentence as BIN1 in open-access papers (continued):
Sharing a sentence is not in itself a finding about the gene and the disease.
BIN1 also shares sentences with these, for which no sentence is quoted: vascular dementia (4 papers); muscle disorders (3); Onset (3); autosomal recessive centronuclear myopathy (2); cardiac arrhythmia (2); cardiac disease (2); Charcot-Marie-Tooth disease (2); depression (2); epithelial ovarian cancer (2); Insulin resistance (2); late-onset Alzheimers disease (2); ulcerative colitis (2); X-linked myotubular myopathy (2); aging (1); and Muscular Disorder (1); Apathy (1); bacterial infection (1); Becker muscular dystrophy (1); behavioral disorders (1); bladder carcinoma (1); brain disorder (1); breast (1); cerebellar ataxia (1); Charcot-Marie-Tooth neuropathies (1); clear cell renal cell carcinoma (1); colorectal cancer (1); coronary heart disease (1); diabetes (1); Duchenne muscular dystrophy (1); early infantile epileptic encephalopathy (1).
A further 27 diseases each share a sentence with BIN1 in 1 paper.